TBILA (TGF-beta induced lncRNA)
Gene: Long non-coding RNA gene on chromosome 3 (112,133,423 to 112,135,359, forward strand). Ensembl gene ENSG00000261488.
Diseases named in the same sentence as TBILA in open-access papers:
TBILA is named in the same sentence as 3 diseases in open-access papers, as found by Europe PMC text mining. Sharing a sentence is not in itself a finding about the gene and the disease. The quoted sentences say what the papers report.
non-small cell lung carcinoma (3 papers, 2020 to 2025). A group of at least three distinct histological types of lung cancer, including non-small cell squamous cell carcinoma, adenocarcinoma, and large cell carcinoma. "Exosomal lncRNAs AGAP2-AS1 and TBILA have also been reported to be overexpressed in non-small cell lung cancer compared with healthy individuals." (PMID 41573685, 2025). "Lu et al28 observed that TBILA (TGFβ‐induced lncRNA) promoted HGAL expression and bound with S100A7 to enhance its carcinogenic effects in non‐small cell lung cancer." (PMID 32583631, 2020).
lymphoma (1 paper, 2019). A malignant (clonal) proliferation of B- lymphocytes or T- lymphocytes which involves the lymph nodes, bone marrow and/or extranodal sites. "TBILA is upregulated by the TGF‐β classical signalling pathway and promotes human germinal centre‐associated lymphoma expression by binding with the Smad transcription factor complex, thereby enhancing RhoA activation." (PMID 30499165, 2019).
tumor (3 papers, 2019 to 2022). "TBILA was significantly correlated with tumor size (p < 0.05), while AGAP2-AS1 was significantly correlated with lymph node metastasis and TNM stage (all, p < 0.05)." (PMID 32015683, 2020). "Given that better stability is a critical prerequisite for tumor biomarkers, we next evaluated the stability of exosomal lncRNA TBILA and AGAP2-AS1 in serum samples." (PMID 32015683, 2020). "In addition, we demonstrated that the levels of TBILA and AGAP2-AS1 were significantly reduced after surgery, which indicates that their levels are related to the presence of the tumor in NSCLC patients." (PMID 32015683, 2020).